MANSC4 (MANSC domain containing 4)
Tractability: Antibody: UniProt predicts a signal peptide or a membrane-spanning region; its Gene Ontology location is reachable by antibodies, with medium confidence.
Gene: Protein-coding gene on chromosome 12 (27,762,427 to 27,780,236, reverse strand). Ensembl gene ENSG00000205693.
Subcellular location: Membrane
Gene Ontology:
Molecular function: serine-type endopeptidase inhibitor activity
Biological process: epidermis development; epithelium development; extracellular matrix organization
Cellular component: plasma membrane; membrane
Genetic constraint (gnomAD): Loss-of-function variants: 11 observed, 12.6 expected, observed/expected ratio (o/e) 0.87, 90% interval 0.55 to 1.44. The upper end of that interval is the gene's LOEUF score, 1.44, which puts it in group 5 of 6, group 1 being the genes least tolerant of losing a copy. Missense variants: 354 observed, 425.22 expected, observed/expected ratio (o/e) 0.83, 90% interval 0.76 to 0.91. Synonymous variants: 123 observed, 155.74 expected, observed/expected ratio (o/e) 0.79, 90% interval 0.68 to 0.92.
Homologues: Orthologues: chimpanzee MANSC4 (99% identical), dog MANSC4 (84% identical), pig MANSC4 (81% identical), rabbit MANSC4 (64% identical), mouse Mansc4 (61% identical), rat Mansc4 (60% identical), tropical clawed frog mansc4 (35% identical). Paralogues in human: MANSC1 (15% identical), C11orf24 (10% identical).
Diseases named in the same sentence as MANSC4 in open-access papers:
MANSC4 is named in the same sentence as 2 diseases in open-access papers, as found by Europe PMC text mining. Sharing a sentence is not in itself a finding about the gene and the disease. The quoted sentences say what the papers report.
diabetes (1 paper, 2024). "Finally, the Mendelian randomization phenome-wide association study corroborated MANSC4 as a reliable target capable of mitigating the risk of various forms of diabetes, and it revealed the absence of adverse effects linked to CTRB1, SIGLEC5 and MST1." (PMID 38931433, 2024).
MANSC4 also shares sentences with these, for which no sentence is quoted: periodontitis (1 paper).